NCAN (neurocan)
Description:
May modulate neuronal adhesion and neurite growth during development by binding to neural cell adhesion molecules (NG-CAM and N-CAM). Chondroitin sulfate proteoglycan; binds to hyaluronic acid.
Synonyms: CSPG3
Tractability: Antibody: UniProt places it where antibodies can reach, with high confidence; its Gene Ontology location is reachable by antibodies, with high confidence; UniProt predicts a signal peptide or a membrane-spanning region. PROTAC: its protein half-life has been measured.
Gene: Protein-coding gene on chromosome 19 (19,211,948 to 19,252,247, forward strand). Ensembl gene ENSG00000130287.
Subcellular location: Secreted
Pathways (Reactome):
Disease: Defective B3GALT6 causes EDSP2 and SEMDJL1; Defective B3GAT3 causes JDSSDHD; Defective B4GALT7 causes EDS, progeroid type; Defective CHST14 causes EDS, musculocontractural type; Defective CHST3 causes SEDCJD; Defective CHSY1 causes TPBS
Metabolism: CS-GAG biosynthesis; CS/DS degradation; DS-GAG biosynthesis; Glycosaminoglycan-protein linkage region biosynthesis
Developmental Biology: L1CAM interactions; NCAM1 interactions
Extracellular matrix organization: ECM proteoglycans
Gene Ontology:
Molecular function: calcium ion binding; hyaluronic acid binding
Biological process: central nervous system development; skeletal system development; cell adhesion
Cellular component: extracellular region; gel phase of interstitial matrix; Golgi lumen; lysosomal lumen; perineuronal net; synapse
Genetic constraint (gnomAD): Loss-of-function variants: 43 observed, 104.71 expected, observed/expected ratio (o/e) 0.41, 90% interval 0.32 to 0.53. The upper end of that interval is the gene's LOEUF score, 0.53, which puts it in group 2 of 6, group 1 being the genes least tolerant of losing a copy. Missense variants: 1,469 observed, 1,684.1 expected, observed/expected ratio (o/e) 0.87, 90% interval 0.83 to 0.91. Synonymous variants: 625 observed, 666.86 expected, observed/expected ratio (o/e) 0.94, 90% interval 0.88 to 1.
Homologues: Orthologues: chimpanzee NCAN (99% identical), macaque NCAN (95% identical), pig NCAN (75% identical), dog NCAN (73% identical), mouse Ncan (66% identical), rat Ncan (66% identical), rabbit NCAN (64% identical), tropical clawed frog ncan (39% identical), zebrafish ncanb (35% identical), zebrafish ncana (16% identical). Paralogues in human: VCAN (31% identical), ACAN (30% identical), BCAN (24% identical), HAPLN3 (11% identical), HAPLN4 (11% identical), HAPLN1 (10% identical), HAPLN2 (10% identical).
Diseases named in the same sentence as NCAN in open-access papers:
NCAN is named in the same sentence as 69 diseases in open-access papers, as found by Europe PMC text mining. Sharing a sentence is not in itself a finding about the gene and the disease. The quoted sentences say what the papers report.
schizophrenia (16 papers, 2014 to 2025). A major psychotic disorder characterized by abnormalities in the perception or expression of reality. "Genome-wide association studies identified a genetic variation in NCAN as a risk factor for bipolar disorder and schizophrenia." (PMID 38512724, 2024). "The NCAN gene variants independently emerged as genome-wide-significant risk loci for bipolar disorder and schizophrenia, as well as a major depressive disorder." (PMID 36631443, 2023). "GWSA studies reviewed here presented the critical importance of NCAN marker (rs1064395 SNP) in identification of BD genetic risk and its possible role in BD association with other psychiatric disorders as schizophrenia and ADHD." (PMID 24955366, 2014). "Many recent studies were focused on genome-wide significant association (GWSA) between variation in the NCAN gene expression and psychiatric disorders such as BD, schizophrenia, and ADHD." (PMID 24955366, 2014). "Also, the presence of NCAN mutants was associated with psychiatric disorders as bipolar disorder, schizophrenia, and ADHD." (PMID 24955366, 2014). "Three loci have been reported to have combined association with both schizophrenia and BD (CACNA1C, CACNB2, and ITIH3-ITIH4), and one locus, which was previously found to be associated with BD (NCAN)." (PMID 34502224, 2021). "Recently, it was shown that some CSPGs members like aggrecan, versican, and neurocan were strongly involved in brain disorders like bipolar disorder (BD), schizophrenia, and ADHD." (PMID 24955366, 2014). "The study results reconfirmed the involvement of NCAN in the visual processing and top-down cognitive activity, with these processes being severely disturbed in patients with schizophrenia." (PMID 24955366, 2014). "Genetic studies have further identified associations of schizophrenia with the genes encoding for the CSPGs neurocan (NCAN) and neuroglycan-C, suggesting that abnormal CSPG expression in schizophrenia may be due, at least in part, to genetic factors." (PMID 26839720, 2016). "Several of these genomic markers are shared between BD and schizophrenia such as CACNA1C, CACNB2, NCAN, TRANK1, ITIH3-ITIH4, and ANK3." (PMID 34502224, 2021).
bipolar disorder (14 papers, 2013 to 2025). A disorder of the brain that causes unusual shifts in mood, energy, activity levels and the ability to carry out day-to-day tasks. "For example, rs1064395 (NCAN) has been reported as a susceptibility factor for bipolar disorder in a GWAS." (PMID 26859814, 2016). "NCAN (neurocan) encodes a chondroitin sulfate proteoglycan potentially involved in the modulation of cell adhesion and migration, and previously linked to bipolar disorder in GWAS and mouse model studies." (PMID 33830993, 2021). "Our studies in cerebral organoids from bipolar disorder showed dysregulation in genes involved in cell adhesion, immune signaling, and endoplasmic reticulum biology; implicated a central role for the GWAS hit NCAN in the biology of BPI; and showed evidence of deficits in neurotransmission." (PMID 32306996, 2020). "Altered NCAN levels or mutations have been associated with SZ, autism spectrum disorder (ASD), and bipolar disorder." (PMID 40282399, 2025). "Previous GWA studies of bipolar disorder have implicated several potential susceptibility genes, such as SYNE1 on chromosome 6q25.2, ODZ4 on 11q14.1, ANK3 on 10q21.2, CACNA1C on 12p13.3, and NCAN on 19p13.1." (PMID 23326512, 2013).
neuroblastoma (10 papers, 2017 to 2025). Neuroblastoma (NB) is the most common solid, extracranial childhood tumor. "NCAN has been associated with poor outcome in neuroblastoma, with NCAN promoting anchorage-independent growth and chemoresistance of neuroblastoma cells." (PMID 37146093, 2023). "NCAN expression is strongly associated with poor prognosis in patients with neuroblastoma (NB)." (PMID 38791985, 2024). "Furthermore, high NCAN expression has been associated with unfavorable outcome in neuroblastoma, as it induces an undifferentiated phenotype that promotes the malignancy." (PMID 32545553, 2020). "Here we observed that high NCAN expression was closely associated with the unfavorable outcome of neuroblastoma (NB)." (PMID 29290949, 2017). "NCAN can promote dedifferentiation of neuroblastoma (NB) cells and can stimulate their malignancy." (PMID 38791985, 2024). "NCAN is mainly expressed in the nervous system and works as an inhibitory molecule to inhibit axon regeneration following a nerve injury, but acts as a promoter for the proliferation of neuroblastoma cells." (PMID 38791985, 2024). "The carcinogenesis and malignancy of neuroblastoma (NB) are influenced by NCAN, which also promotes the growth and invasion of glioma cells." (PMID 38455474, 2024). "Additionally, overexpression of NCAN protein has been reported in neuroblastoma." (PMID 35202840, 2022). "A recent study demonstrated that a signature consisting of five genes (AKR1C2, NCAN, AHCY, FBP2 and GALNT3) has potential prognostic values in neuroblastoma." (PMID 36701414, 2023). "In neuroblastoma (NB), the CSPG NCAN is highly expressed in the tumor ECM where it facilitates growth of NB cells and promotes disease progression." (PMID 32231047, 2020).
glioma (9 papers, 2016 to 2025). A benign or malignant brain and spinal cord tumor that arises from glial cells (astrocytes, oligodendrocytes, ependymal cells). "By comparison, SF10345 showed a progressive up‐regulation of genes encoding extracellular matrix and transmembrane proteins associated with glioma motility and invasion, such as tenacin‐C, neurocan, and integrin." (PMID 27888226, 2016). "Regarding glioma cell migration, the extracellular matrix of the brain contains large quantities of specific molecules (e.g., neurocan and brevican (lectins) and phosphocan), which are secreted by astrocytes and oligodendrocytes and play a promigratory role." (PMID 39153088, 2024). "NCAN expression promotes also glioma cell proliferation and invasion through the Rho/Rho-associated protein kinase pathway." (PMID 37146093, 2023). "Because tumor sphere cells in gliomas, breast cancer and colon cancer showed increased stemness and malignancy, we investigated the phenotype of those NCAN-expressing tumor sphere cells." (PMID 29290949, 2017). "NCAN can potentially serve as a target for glioma therapy and a prognostic marker." (PMID 38791985, 2024). "The prominent upregulation of NCAN and VCAN in resistant Y79 cells might also correlate with their role in tumor growth and invasion as it has been demonstrated in glioma and in lung carcinoma." (PMID 32560557, 2020).
steatosis (5 papers, 2014 to 2025). Increased lipid within the cytoplasm of cells. "The variant in NCAN was significantly associated with increased histological features of steatosis, lobular inflammation and perivenular fibrosis, and trended towards increased ballooning." (PMID 26462272, 2015). "In this group, CD63 and CD38 positively correlated with steatosis grade, while NCAN and BCAN positively correlated with bioimpedance values." (PMID 39407757, 2024). "We can assume that NCAN rs2228603 is mainly involved in the progress of NASH by influence liver damage based on simple steatosis." (PMID 27887608, 2016).
dyslexia (4 papers, 2017 to 2025). A learning disorder characterized by an impairment in processing written words. "Moreover, the right temporoparietal region associated with rs1064395 in NCAN and also overlapped with a region previously associated with the dyslexia susceptibility genes KIAA0319, DYX1C1 and MRPL19, as well as CEP63." (PMID 34068951, 2021). "Common variants implicating NCAN are associated with cognitive performance and limbic gray matter volumes in healthy individuals, while a rare variant is associated with dyslexia." (PMID 30930738, 2019). "NCAN is expressed in several tissues, including several brain areas; its expression was significantly correlated with that of two other dyslexia candidate genes, namely GRIN2B and KIAA0319." (PMID 34068951, 2021).
liver disease (4 papers, 2016 to 2025). "For instance, hyaluronic acid is a liver disease biomarker, the protein NCAN binds with hyaluronic acid thus reduces liver cirrhosis." (PMID 37034613, 2023). "Their frequency was less common in the Mexican population, which might hide their influence on liver disease, given the well-established role of TM6SF2 and NCAN variants in liver disease." (PMID 40806538, 2025).
mild cognitive impairment (3 papers, 2021 to 2024). "In a proteomic analysis, NCAN, BCAN, CTSS, MSR1, MDGA1, and CPA2 were reported as upregulated in individuals with PTSD and comorbid mild cognitive impairment." (PMID 35625844, 2022).
astrocytoma (2 papers, 2020 to 2024). "NCAN is expressed abundantly in developing rat retina, and in Müller cells correlate with the invasive phenotype in low-grade astrocytoma." (PMID 32545553, 2020). "NCAN is significantly increased in astrocytoma, glioblastoma, and other tumours." (PMID 38791985, 2024). "The invasiveness of low-grade astrocytoma is primarily attributed to BCAN, NCAN, Tenascin-C, and VCAN." (PMID 38791985, 2024).
autism (2 papers, 2013 to 2018). Persistent deficits in social interaction and communication and interaction as well as a markedly restricted repertoire of activity and interest as well as repetitive patterns of behavior. "Some of the genes, such as NCAN and EPHA7, have similar functionality as NRXN1 in mediating neuronal cell interactions, while some other genes, such as PCDH19, CNTN3, CTNNA3, LMX1B, are known autism candidate genes." (PMID 23536886, 2013).
cognitive decline (2 papers, 2020 to 2022). "It is not yet known what role CSPGs and the PNN may play in age-related cognitive decline; however, our data suggest that NCAN and BCAN are associated with brain volume and may potentially play a neuroprotective role for general fluid cognitive ability in early adulthood." (PMID 32041957, 2020). "The lack of NCAN has been associated with cognitive decline and diminished brain volumes in the elderly." (PMID 35928685, 2022).
dementia (2 papers, 2024 to 2025). Loss of intellectual abilities interfering with an individual's social and occupational functions. "Our findings included well-known dementia-associated protein biomarkers, such as BMP4, CD200, MANF, PLXNB1, PLXNB3, and SMPD1 for AD and BCAN, NCAN, and THY1 for VD, as well as uncovering novel proteins associated with AD or VD." (PMID 39226887, 2024). "Our findings also covered well-known dementia-associated proteins, such as BCAN, CNTN5, and NCAN, along with identifying recently promising biomarkers, including IL18, MMP12, TNFSF12, and UNC5C, where these biomarkers presented the highest protein importance in their clusters." (PMID 40748327, 2025).
Epilepsies (2 papers, 2016 to 2023). "The deficits of PNNs measured by reduced WFA numbers and decreased tenascin-R, aggrecan and neurocan protein levels might be related to the pathophysiology of epilepsy induced by PTZ." (PMID 27880801, 2016). "Epilepsies with a genetic basis can manifest early in life, and both BCAN and NCAN are believed to play crucial roles in terminal differentiation during development, as well as in the adult nervous system during postnatal development." (PMID 36980356, 2023).
hepatocellular carcinoma (2 papers, 2024 to 2025). A malignant tumor that arises from hepatocytes. "NCAN rs2228603 polymorphism T allele was significantly higher in patients with hepatocellular carcinoma (HCC) due to alcoholic liver disease (ALD) and may serve as a risk factor." (PMID 38791985, 2024).
hyperlipidemia (2 papers, 2020 to 2024). "We also confirmed a causal relationship between APOB, PCSK9, and NCAN and hyperlipidemia in the external dataset." (PMID 39474612, 2024). "Although the PPI results showed that NCAN is an isolated node, it is also worth noting that the interaction between NCAN and the environment has been linked to hyperlipidemia, and these studies further support the results of our study." (PMID 39474612, 2024). "Validating the primary results by using the same significant variant strategies across different datasets, we observed that NCAN was associated with hyperlipidemia in two external datasets." (PMID 39474612, 2024). "Additionally, NCAN showed weakly significant causality for hyperlipidemia in the FinnGen cohort." (PMID 39474612, 2024). "For example, using the SNPs reported in seven studies as genetic instrumental variables, the risk of hyperlipidemia was augmented by increased APOB (OR = 3.28; 95% CI, 1.78–6.04; P = 1.44e-04), NCAN (OR = 1.41; 95% CI, 1.16–1.71; P = 4.73e-04), and PCSK9 (OR = 1.39; 95% CI, 1.25–1.54; P = 1.00e-09)." (PMID 39474612, 2024). "Herein, we report three potential drug-targeting proteins for hyperlipidemia: PCSK9, APOB, and NCAN." (PMID 39474612, 2024). "The genotypic and allelic frequencies of 12 SNPs in the NCAN, TM6SF2, CILP2, PBX4, SUGP1 and MAU2 were substantially different between the hyperlipidemia and normal groups." (PMID 32568739, 2020). "In conclusion, this study shows potential interactions among the NCAN, TM6SF2, CILP2, PBX4, SUGP1 and MAU2, environment and serum lipid levels in hyperlipidemia subjects." (PMID 32568739, 2020). "The incidences of the NCAN C-C (G2), TM6SF2 T-A (G3), TM6SF2 C-A (G5), CILP2 G-T (G6), PBX4-SUGP1 G-C (G8), MAU2 G-G-G-C (G9), MAU2 G-A-G-C (G10), MAU2 C-G-A-T (G12), and MAU2 C-A-G-T (G13) haplotypes were significantly different between the hyperlipidemia and normal groups (P < 0.05 for all)." (PMID 32568739, 2020).
ischemic stroke (2 papers, 2021). A stroke disorder caused by obstruction of blood flow to the brain, due to thrombotic (local blood clot formation) or embolic (due to a blood clot or other material traveling from another site) event. "Our current studies further clarified that the reduced GFAP, neurocan, and phosphacan expressions are not simply due to the reduced brain injury in the acute stage of ischemic stroke with RIPK inhibition." (PMID 33629276, 2021).
mental disorder (2 papers, 2014 to 2025). A disease that has its basis in the disruption of mental process. "Accordingly, clinical and in silico studies focused on drugs involved in psychiatric disorders treatment as well as in reducing CSPGs (NCAN, ACAN, and VCAN) activity are presented in the next section." (PMID 24955366, 2014). "Unfortunately, the mechanism by which NCAN (rs1064395) SNP could be involved in these psychiatric disorders is still unclear." (PMID 24955366, 2014).
Merkel Cell Carcinoma (2 papers, 2023 to 2024). "Low NCAN expression was associated with lower Merkel Cell Carcinoma (MCC)-specific survival compared with NCAN intermediate- and high-expression groups (p = 0.044)." (PMID 38791985, 2024). "Increased NCAN expression is associated with improved survival rates in Merkel cell carcinoma (MCC), though the specific mechanisms are yet to be elucidated." (PMID 38791985, 2024). "NCAN expression in 144 Merkel cell carcinoma samples on tissue microarray." (PMID 37146093, 2023).
multiple sclerosis (2 papers, 2016 to 2020). A progressive autoimmune disorder affecting the central nervous system resulting in demyelination. "The upregulation of versican V2, aggrecan, and neurocan as CSPGs family members, following multiple sclerosis, was also reported by Sobel & Ahmed (2001)." (PMID 32483473, 2020).
nonalcoholic fatty liver disease (2 papers, 2016 to 2024). "An instrumental variable of NCAN, rs2228603, was associated with nonalcoholic fatty liver disease." (PMID 38762700, 2024).
Alzheimer disease (1 paper, 2024). A progressive, neurodegenerative disease characterized by loss of function and death of nerve cells in several areas of the brain leading to loss of cognitive function such as memory and language. "Genetic variation in the gene encoding A Disintegrin and Metalloproteinase with Thrombospondin Motifs 4 (ADAMTS4), which degrades the four members of the lectican family (including NCAN and BCAN), has been implicated in Alzheimer’s disease." (PMID 38762535, 2024). "Taken together, the evidence suggests NCAN, BCAN and their regulators as molecules-of-interest in Alzheimer’s disease." (PMID 38762535, 2024).
atherosclerosis (1 paper, 2016). A disease characterized by the build-up of fatty material and calcium deposition in the arterial wall resulting in partial or complete occlusion of the arterial lumen. "HDL is negatively related to the incidence of atherosclerosis and a decreased level of HDL might indicate the clinical damage to liver cells, while we could not deny the possible influence of the elevated HDL-cholesterol on the association between NCAN and NAFLD among different population." (PMID 27887608, 2016).
cerebral malaria (1 paper, 2024). A sequestration of Plasmodium falciparum in the brain, which can cause coma and/or seizures. "We observed that the corresponding RNA from GFAP and NCAN in plasma EVs from patients with cerebral malaria increased with disease trajectory." (PMID 39151016, 2024).
cyst (1 paper, 2024). A sac-like closed membranous structure that may be empty or contain fluid or amorphous material. "Neurocan expression was confirmed in the cyst area (yellow dotted line) along with GFAP-positive cells." (PMID 38650015, 2024).